GATA6 (GATA binding protein 6)
Diseases named in the same sentence as GATA6 in open-access papers (continued):
Sharing a sentence is not in itself a finding about the gene and the disease.
squamous cell carcinoma (5 papers, 2017 to 2025). A carcinoma arising from squamous epithelial cells. "Squamous cell carcinomas showed frequent genic amplification of CCND1 and SOX2 and/or TP63, while ERBB2, VEGFA, GATA4, and GATA6 were more commonly amplified in adenocarcinomas." (PMID 37893095, 2023). "Squamous cell carcinomas showed frequent genomic amplifications of CCND1 and SOX2 and/or TP63, whereas ERBB2, VEGFA and GATA4 and GATA6 were more commonly amplified in adenocarcinomas." (PMID 28052061, 2017). "Currently, no studies have explored the mechanism of GATA6 in PSCC, but its critical role in squamous cell carcinoma at other sites has been investigated." (PMID 40657383, 2025). "In contrast, squamous cell carcinomas (SCC), HF/matrical tumors, and extramammary Paget's disease (EMPD) were negative for Gata6." (PMID 30886049, 2019).
Barrett esophagus (4 papers, 2008 to 2021). Esophageal lesion lined with columnar metaplastic epithelium which is flat or villiform. "GATA6 amplification increases during the progression from normal esophageal squamous epithelia to Barrett’s metaplasia and finally to the invasive EAC." (PMID 33300112, 2021).
congenital diaphragmatic hernia (4 papers, 2020 to 2025). A posterolateral defect of the diaphragm that allows passage of abdominal viscera into the thorax, leading to respiratory insufficiency and persistent pulmonary hypertension with high mortality. "Pancreatic agenesis/hypoplasia or congenital diaphragmatic hernia occurred in 20/70 patients (28.5%) and more frequently with GATA6 LoF (14/27) than missense (9/43) variants (p=0.001)." (PMID 33054971, 2020). "As damaging variants in these genes cause congenital diaphragmatic hernia, these data imply that GATA6 haploinsufficiency causes diaphragmatic dysgenesis by disrupting NR2F2 and ZFPM2 gene programs." (PMID 33054971, 2020). "Our analyses support the conclusion that CHD, pancreatic malformations and congenital diaphragmatic hernia that occur in GATA6 exon four missense mutants reflect both loss of physiologic levels of GATA6 and excessively activated RA signaling." (PMID 33054971, 2020). "While often informative, prior studies of mice with one inactivated Gata6 allele have either subtle dysmorphic aortic valves or no CHD and notably lack pancreatic agenesis or congenital diaphragmatic hernia that occur in human CHD patients with damaging GATA6 variants." (PMID 33054971, 2020). "The selective transcriptional deficits evoked by these variants provides mechanistic insights into the high prevalence of particular heart malformation and associated pancreatic dysgenesis and congenital diaphragmatic hernias that occur in CHD patients with pathogenic GATA6 variants." (PMID 33054971, 2020).
embryonal carcinoma (4 papers, 2011 to 2017). A non-seminomatous malignant germ cell tumor characterized by the presence of large germ cells with abundant cytoplasm resembling epithelial cells, geographic necrosis, high mitotic activity, and pseudoglandular and pseudopapillary structures formation. "Stat-3 and Ras pathways have been implicated in the control of GATA-4 expression in embryonal carcinoma and ES cells, and experiments using GATA-6 knockout and chimeric mice suggest a cross-regulation between GATA-6 and GATA-4." (PMID 23409073, 2013).
Infertility (4 papers, 2017 to 2023). "In addition, the loss of GATA4 and GATA6 using knockout technology can lead to abnormal ovarian structure and infertility, including oocyte reduction and ovulation failure." (PMID 28275215, 2017). "In female mice, the loss of GATA4 and GATA6 resulted in failed ovulation and infertility." (PMID 28275215, 2017). "The loss of GATA6 and GATA4 resulted in failed ovulation and infertility, and negatively affected the development of granulosa cells." (PMID 36617567, 2023). "GATA4 and GATA6 knockout female mice exhibited infertility due to disrupted formation of ovaries." (PMID 34107878, 2021).
liver cancer (4 papers, 2020 to 2024). An epithelial or non-epithelial malignant neoplasm that arises from the liver. "The low expression of miR-143 in liver cancer patients targets the regulation transcription factor GATA-binding factor 6 (GATA6) to inhibit the growth and invasion of liver cancer cells." (PMID 38584703, 2024).
Obesity (4 papers, 2021 to 2025). Accumulation of substantial excess body fat. "Here, we showed that Gata6 and Samd4b are upregulated during adipocyte differentiation, which supports a role for these genes in predisposing offspring of obese fathers to diet-induced obesity in later life." (PMID 33479343, 2021). "However, additional experiments are needed to functionally validate the role of Gata6 and Samd4b in non-genetic transmission of paternal obesity." (PMID 33479343, 2021).
Ovarian tumor (4 papers, 2009 to 2022). "Ovarian tumours in wild-type mice had an elevated content of F4/80+GATA-6+ and F4/80+GATA-6– macrophages, whereas healthy ovaries contained only F4/80+GATA-6– macrophages, a finding confirmed by confocal microscopy." (PMID 32246014, 2020). "Moreover, some studies reported that methylation in the GATA4 and GATA6 promoter region could play an important role in ovarian carcinogenesis, elevated GATA4 and lower GATA6 mRNA levels are associated with better prognosis in ovarian tumours." (PMID 35488350, 2022).
asthma (3 papers, 2023 to 2025). "GATA6 exhibits an inverse correlation with the expression of Caveolin-1 in mouse models of asthma and silencing of GATA6 upregulates Caveolin-1 expression." (PMID 36918760, 2023). "Moreover, downregulation of GATA6 has been shown to reduce inflammation, infiltration, and mucus production by inhibiting TLR2 signaling in asthma models." (PMID 39897029, 2025). "As a result, they could be bonded asthma-related proteins, such as AR, FOXA1, GATA3, and GATA6." (PMID 37569643, 2023).
bladder cancer (3 papers, 2021 to 2025). "ZNF503-AS1 acts as a tumor suppressor in bladder cancer by recruiting transcription factor GATA6 to up-regulate SLC8A1, which increases intracellular Ca2+ concentration." (PMID 40909272, 2025). "In one study, it was observed that lncRNA ZNF503-AS1 interacted with GATA6 to modulate the expression of calcium channel protein SLC8A1 in bladder cancer." (PMID 41514651, 2025).
breast tumor (3 papers, 2017 to 2025). "Of clinical relevance, we first quantified the expression of GATA6 and TET1 in breast tumors and adjacent normal breast tissues." (PMID 40216762, 2025). "In the SQ breast tumors, we observed significantly upregulated mRNA levels of the Oct3/4 regulatory network, including ONSS, and several other PTFs, including Nanog, Sall4, Sox2, Sox4, FoxA2, Gata6, Zic2 and HoxB7, as well as Oct3/4 isoform B, polycomb suppressors Bmi1, EzH2, Amigo and Dkk1." (PMID 37298091, 2023).
cardiomyopathy (3 papers, 2016 to 2019). A disease of the heart muscle or myocardium proper. "Decreased or elevated expression of the GATA6 gene has been reported to be associated with many cardiovascular diseases in humans, such as CHD, arrhythmia, cardiomyopathy, and neonatal and adult diabetes." (PMID 31781165, 2019).
esophageal cancer (3 papers, 2014 to 2023). A primary or metastatic malignant neoplasm involving the esophagus. "Another example is involved in the research of esophageal cancer, the combination of the genes GATA6 and SPRR3 may discriminate among normal epithelium, Barrett's dysplasia and Barrett's esophagus associated AC." (PMID 24743794, 2014). "Some special relationships exist between the gene pair (GATA6 and SPRR3) and the phenotypes of esophageal cancer." (PMID 24743794, 2014).
exocrine pancreas insufficiency (3 papers, 2022 to 2024). "The identification of the pathogenic variant in GATA6 allowed us to perform a diagnosis of exocrine pancreatic insufficiency." (PMID 39596087, 2024). "Exocrine pancreatic insufficiency is typical for patients with pathogenic variants of the GATA6 gene, and the level of fecal elastase-1 was studied, and a decrease in the indicator was found (35 μg/g, with a normal level of >200)." (PMID 39596087, 2024). "According to the literature, the early diagnosis and therapy of exocrine pancreatic insufficiency and insulin therapy had a positive effect on the growth prognosis in patients with GATA6 gene variants and was confirmed in our clinical case." (PMID 39596087, 2024). "The subsequent growth of patients is normal or below average, which also may be associated with nutritional deficiency due to exocrine pancreatic insufficiency, a common component of GATA6 syndrome." (PMID 39596087, 2024). "Screening for other possible components of GATA6 syndrome revealed exocrine pancreatic insufficiency, and pancreatic enzyme replacement therapy resulted in improved dyspeptic symptoms, and growth rates increased." (PMID 39596087, 2024). "We report a novel heterozygous variant of a 4-nucleotide deletion (c.1302+4_1302+7del) in the donor splicing site of exon 3 of the GATA6 gene in a patient of the age of 8 with neonatal diabetes, exocrine pancreatic insufficiency, gallbladder atresia, and a congenital heart defect." (PMID 39596087, 2024).
glioma (3 papers, 2014 to 2017). A benign or malignant brain and spinal cord tumor that arises from glial cells (astrocytes, oligodendrocytes, ependymal cells). "Our results indicate that similarly to gliomas, GATA6 promoter is also methylated in meningiomas, however, with significantly lower frequency (13.64 vs 30–68 % in glioma)." (PMID 25648363, 2015). "Recently, GATA6 gene was found to be frequently methylated in glioma patients." (PMID 25648363, 2015). "To identify which transcription factor is a potent regulator for CYP17A1 transcription in glioma, we analyzed the correlation of CYP17A1 with NFIC, Sp1, Sp3 or GATA6 in complementary DNA microarray database of glioma." (PMID 28530704, 2017). "Our previous study has shown that a panel of 12 genes including ERCC1, hMLH1, ATM, CDKN2B (p15INK4B), p14ARF, CDKN2A (p16INK4A), RASSF1A, RUNX3, GATA6, NDRG2, PTEN, and RARβ might be useful in evaluation of glioma aggressiveness." (PMID 25648363, 2015). "DCA decreased the expression of Taldo, Stat3, Sox2 and Gata6 in glioma spheroids but not in NSCs." (PMID 24481450, 2014).
Inguinal hernia (3 papers, 2016 to 2025). Protrusion of the contents of the abdominal cavity through the inguinal canal. "Genetic studies from China revealed that DNA sequence variants (DSVs) might contribute to inguinal hernia development by changing the transcriptional activities of TBX1, TBX2, TBX3, Sirtuin 1, and GATA transcription factor 6 (GATA6) gene promoters." (PMID 31024927, 2019).
liver fibrosis (3 papers, 2020 to 2025). "Among the corresponding transcription factors, GATA6, SOX4, and SOX9 have been reported to be associated with liver fibrosis." (PMID 32442221, 2020). "Recently, the transcription factors GATA-binding factor 6 (GATA6) and transcription factor 21 (Tcf21) were identified as factors inhibiting profibrotic HSCs, thereby promoting liver fibrosis regression." (PMID 35805998, 2022). "Furthermore, the expression of peroxisome proliferator-activated receptor (PPAR)γ, GATA-binding factor 6 (GATA6), GATA4, and transcription factor 21 (TCF21) appears to play a role in regulating HSC reversion to an inactive state in liver fibrosis 42-44." (PMID 39897543, 2025).
lung squamous cell carcinoma (3 papers, 2020 to 2025). "In lung squamous cell carcinoma, GATA6 has a binding site in the promoter region of plasminogen activator urokinase (PLAU), and GATA6 inhibits PLAU transcription by binding to PLAU promoter region, down-regulating PLAU expression, thereby inhibiting the cancer-promoting effect of PLAU50." (PMID 40657383, 2025).
metastatic tumor (3 papers, 2021 to 2024). "GATA6+ LPM can invade liver malignant tumors and contribute to metastatic tumor growth and recurrence." (PMID 39192982, 2024). "Recently a novel suppressive function of GATA6 has been described within gastric adenocarcinoma revealing that patients with metastatic tumors had low GATA6 expression with a negative impact on the patients’ survival." (PMID 33300112, 2021). "It should be noted that in metastatic disease treated with gemcitabine regimens, differences in OS based on GATA6 expression could not be demonstrated either." (PMID 36830789, 2023).
neonatal diabetes mellitus (3 papers, 2017 to 2024). Neonatal diabetes mellitus presents as hyperglycemia, failure to thrive and, in some cases, dehydration and ketoacidosis which may be severe with coma, in a child within the first months of life. "Mutations in GATA6 are associated with human pancreas agenesis, and mutations in GATA4, and MNX1 cause permanent neonatal diabetes mellitus." (PMID 39322760, 2024).
retinoblastoma (3 papers, 2021 to 2022). A malignant tumor that originates in the nuclear layer of the retina. "Hypoxia-induced miR-181b promoted the angiogenesis of retinoblastoma (Rb, a malignancy originating from the retina) by downregulating programmed cell death-10 (PDCD10) and GATA binding protein 6 (GATA6)." (PMID 35626707, 2022). "One group identified that miR-181b was increased in retinoblastoma cells and enhanced angiogenesis through targeting programmed cell death-10 (PDCD10) and GATA binding protein 6 (GATA6)." (PMID 34356894, 2021). "Upregulation of miR-181b which is induced by hypoxia could increase angiogenesis of retinoblastoma cells by regulating PDCD10 and GATA6." (PMID 35402235, 2022).
adrenal tumors (2 papers, 2014 to 2019). "Unlike the reciprocal expression pattern of GATA4 and GATA6 in adrenal tumors, expression of GATA4 and GATA6 positively correlated with each other at both mRNA and protein levels in tumor and peritumor tissues (data not shown)." (PMID 24498120, 2014).
astrocytic tumor (2 papers, 2020 to 2022). A glial tumor of the brain or spinal cord showing astrocytic differentiation. "GATA6 is also a tumor suppressor, and deletions or mutations are frequently found in high-grade astrocytic tumors." (PMID 36703629, 2022). "Besides, based on expression, loss of heterozygosity and loss function analysis, GATA6 low‐expressed in tumour, and researcher indicated that GATA6 was a new tumour suppressor gene in astroglioma." (PMID 32757451, 2020).
Atrioventricular septal defects (2 papers, 2016 to 2025). "Atrioventricular septal defects (AVSD) are a rare cardiac malformation associated to date with a handful of canonical genes in cardiac development (NKX2-5, GATA4, GATA6, CRELD1) and may co-occur with certain rare syndromes." (PMID 27058611, 2016).
basal cell carcinoma (2 papers, 2019). A carcinoma involving the basal cells. "Reciprocally, switching off GLI activity in basal cell carcinoma of the skin was associated with a cell identity switch involving induction of GATA6." (PMID 31134896, 2019). "Gata6 specifically marks human SG tumors and also defines tumors with elements of sebaceous differentiation, including a subset of basal cell carcinomas." (PMID 30886049, 2019).
colon adenoma (2 papers, 2008 to 2015). An adenoma that arises from the colon. "In line with our previous findings, GATA6 has been shown to drive the expression of LGR5 in colon adenoma stem cells." (PMID 26387746, 2015). "Furthermore, it has been reported that Gata6 deletion in an Apc-null background, a mouse model of intestinal tumorigenesis, leads to prolonged survival, lower intestinal tumor burden and a decrease in the self-renewal capacity of colon adenoma stem cells." (PMID 26387746, 2015).
coronary artery disease (2 papers, 2021). "Indeed, our results are consistent with the reversible expression of GATA6 by LpM in the absence of sustained retinoic acid receptor signaling and mirror recent findings that pericardial cavity GATA6+ macrophages lose expression of GATA6 following recruitment to areas of ischemic heart disease." (PMID 33536334, 2021). "This present study aims to identify the expression patterns of miR-10a/GATA6/VCAM-1 in vivo and study their implications in the pathophysiology of human coronary artery disease (CAD)." (PMID 34336268, 2021).
gastric adenocarcinoma (2 papers, 2020 to 2021). "In genomics, ERBB2, VEGFA, GATA4 and GATA6 gene amplifications were frequently observed in Barrett’s adenocarcinomas, which strongly resemble the chromosomally unstable variant of gastric adenocarcinoma." (PMID 33087057, 2020).
gastric tumors (2 papers, 2024 to 2025). "Thus, GATA6 may function as a differentiation factor in certain gastric tumors, and its presence in distal tumors could help maintain an epithelial phenotype that restrains aggressiveness." (PMID 40862793, 2025).
heart abnormalities (2 papers, 2024 to 2025). "Herein, we performed genotypic–phenotypic analyses in two probands affected with novel GATA5 and GATA6 variants and congenital heart abnormalities, mostly affecting the right cardiac structures." (PMID 40076735, 2025).
hyperglycaemia (2 papers, 2021 to 2024). "Our results of the long-term observation of a child with GATA6 syndrome with neonatal transient hyperglycemia that recurred in childhood expand the knowledge about the genetic and clinical features of patients with GATA6 syndrome." (PMID 39596087, 2024). "Genetic deletion of either Pax6 or Gata6 results in hyperglycaemia and decreases the expression of several β-TFs and regulators of GSIS." (PMID 33989778, 2021).
hypertrophic cardiomyopathy (2 papers, 2016 to 2017). A condition in which the myocardium is hypertrophied without an obvious cause. "By querying the SNP function prediction web site, we found that rs11210278 (caTAATCgag) is a potential binding site for GATA6, which is a transcription factor involved in hypertrophic cardiomyopathy." (PMID 28882114, 2017). "Overexpression of Gata6, a zinc finger transcription factor that regulates embryogenesis during vertebrate development, induces hypertrophic cardiomyopathy in mice." (PMID 27331400, 2016).
idiopathic pulmonary fibrosis (2 papers, 2019 to 2023). Idiopathic pulmonary fibrosis (IPF) is a nonneoplastic pulmonary disease that is characterized by the formation of scar tissue within the lungs in the absence of any known cause. "Two are associated with pulmonary fibrosis (NKX2-1 and GATA6), another is involved in various cellular stress signaling pathways (ATF5)." (PMID 37206915, 2023).
inflammatory bowel disease (2 papers, 2019 to 2024). A spectrum of small and large bowel inflammatory diseases of unknown etiology. "Among the 57 confirmed hits, we brought out the TLR5-MYD88 signaling pathway, but above all new signaling proteins, epigenetic regulators and transcription factors so far unrevealed in the HBD2 regulatory circuits, like the GATA6 transcription factor involved in inflammatory bowel diseases." (PMID 38965312, 2024).
microtia (2 papers, 2020 to 2021). "Currently, mutations in GATA6 were reported to be associated with microtia in Awassi sheep in ruminants." (PMID 34680890, 2021). "A duplication mutation in ECR near HMX1 modified by a SNP in GATA6 exon seven plays a significant role in Awassi sheep microtia." (PMID 32481741, 2020). "Results showed mutations in only two genes significantly associated with microtia in Awassi: duplication in part of ECR near HMX1 (6:114293121-6:114293196) and a SNP at GATA6 exon 7 (23:34498242)." (PMID 32481741, 2020). "Association results revealed that the ECR locus accounts for the microtia phenotype, while GATA6 exon 7 acts as a modifier gene." (PMID 32481741, 2020).